LINC02195 (long independently transcribed non-coding RNA 2195)
Gene: Long non-coding RNA gene on chromosome 16 (26,584,755 to 26,598,192, reverse strand). Ensembl gene ENSG00000236481.
Diseases named in the same sentence as LINC02195 in open-access papers:
LINC02195 is named in the same sentence as 2 diseases in open-access papers, as found by Europe PMC text mining. Sharing a sentence is not in itself a finding about the gene and the disease. The quoted sentences say what the papers report.
head and neck squamous cell carcinoma (1 paper, 2022). A squamous cell carcinoma that arises from any of the following anatomic sites: lip and oral cavity, nasal cavity, paranasal sinuses, pharynx, larynx, and salivary glands. "Among them, LINC02195 is reported as a favorable prognostic marker in head and neck squamous cell carcinoma." (PMID 35165206, 2022).
tumor (1 paper, 2022). "Interestingly, we discovered that LINC02195 was up-regulated in the low-risk group and correlated to a favorable prognosis of BC patients in this research, suggesting that LINC02195 may act as a tumor suppressor and plays an important role in the immunity of BC." (PMID 36425941, 2022).